GDF15 (growth differentiation factor 15)
Diseases named in the same sentence as GDF15 in open-access papers (continued):
Sharing a sentence is not in itself a finding about the gene and the disease.
tumor (continued). "Mechanistically, tumor-derived GDF-15 was reported to suppress proapoptotic macrophage activity by inhibiting NF-κB signaling via TGF-beta-activated kinase (TAK1), thereby blocking the synthesis of TNF-α and nitric oxide (NO) production." (PMID 32508832, 2020). "Evidence indicates that GDF-15 plays different roles in different stages of tumor progression, by acting on the Smad signaling pathway." (PMID 33193874, 2020). "At necropsy, isotype control antibody treated MIC-1fms mice had significantly smaller tumor than isotype control antibody treated WT mice (p<0.0001), consistent with the previously reported actions of GDF15." (PMID 32502202, 2020). "To explore the physiological functions of upregulated GDF15 in the setting of hypoxia, we investigated the role of GDF15 in tumor cell metastasis, which is highly promoted upon hypoxia." (PMID 32076610, 2020). "Similar to macrophages in white adipose tissue also macrophages in the tumor microenvironment adopt a tolerogenic/immunosuppressive phenotype when exposed to GDF-15." (PMID 32508832, 2020). "Subsequent studies have shown that BM stromal cells produce GDF-15 after direct contact with tumor cells, while GDF-15 strongly enhances their clonogenic growth and self-renewal (T.)." (PMID 33144847, 2020). "GDF15 is expressed much more in tumor tissues of CRC patients and displays positive correlations with CHOP and HIF1α in mRNA levels." (PMID 32076610, 2020). "This GDF15 mediated protection from tumor growth is even more marked when the orthotopically engrafted cells come from TRAMPrag-/- whose tumor has not undergone editing by the immune system prior to engraftment." (PMID 32502202, 2020). "Tumor weight analysis revealed that the GDF15-KD tumors were substantially larger than the control tumors." (PMID 33086658, 2020). "For instance, in GDF15-NT tumor, interferon signaling, and G2/M DNA damage checkpoint regulation were highly up-regulated after cisplatin treatment." (PMID 33086658, 2020). "To investigate the GDF15 expression levels in tumors of CRC patients, we analyzed the pattern of GDF15 expression in both tumor tissues and matched peritumor tissues from 21 CRC patients." (PMID 32076610, 2020). "In chemical models of colon and lung carcinogenesis, transgenic overexpression of human GDF15 suppressed tumor formation." (PMID 32310257, 2020). "After being subjected to starvation and then exogenous fatty acid treatment, tumor cells with GDF15 overexpression displayed robustly enhanced maximal respiration and burned much more fatty acids to supply energy." (PMID 32076610, 2020). "To further investigate the impact of knocking down GDF15 in the tumor formation by A2780 in nude mice, we performed RNAseq analysis of GDF15-NT A2780 and GDF15-KD A2780 tumors from mice treated with PBS or cisplatin." (PMID 33086658, 2020). "Like the data from transgenic TRAMP mice, the orthotopic tumor size data suggests that the GDF15 mediated protection from growth of engrafted TRAMP tumors requires intact adaptive immunity." (PMID 32502202, 2020). "After tumor bearing mice were treated with cisplatin treatment, the decrease in tumor weight was more drastic in the GDF15-KD A2780 tumors than the control GDF15-NT A2780 tumors, suggesting that GDF15 induction increases tumor resistance to cisplatin." (PMID 33086658, 2020). "The increase of GDF-15 in aggressive disease and recurrence has been reported in gene- expression signatures from circulating tumor cells, further emphasizing our findings." (PMID 30645608, 2019). "GDF‐15 represents a promising target for our pathophysiologic understanding in cardio‐oncology linking conditions of both cardiac and neoplastic disease." (PMID 31463975, 2019).
tumor (continued). "The expression level of GDF‐15 mRNA was significantly higher in tumor tissues than in normal tissues, with a standard mean difference (SMD) of 0.79% and a 95% confidence interval (95% CI) of 0.63–0.95." (PMID 30652072, 2019). "Here, we found that GDF15 is an important mediator of TK1 function, as the TK1 knockdown-induced reduction in LUAD tumor growth and metastasis can be rescued by ectopic expression of GDF15." (PMID 31589613, 2019). "Collectively, these results demonstrate that TK1 promotes LUAD tumor growth, in part, by stimulating the expression of GDF15." (PMID 31589613, 2019). "In the present study, it was found that GDF‐15 mRNA was significantly increased in GC tumor tissues compared with normal gastric tissues, while GDF‐15 protein was over‐expressed in the blood of GC patients compared with healthy controls." (PMID 30652072, 2019). "We demonstrated correlation between plasma GDF-15 and MRI determined tumor size and cervical infiltration." (PMID 30645608, 2019). "We further show that knockdown of TK1 inhibits tumor growth and metastatic attributes by inhibiting Rho GTPase activity and by reducing the expression of growth and differentiation factor 15 (GDF15)." (PMID 31589613, 2019). "GDF15 has also been shown to protect transformed cells from macrophages, to promote tumor development in vivo, to regulate bone metastasis, and to induce LUAD cell proliferation." (PMID 31589613, 2019). "Patients with high plasma level of GDF-15 had significantly larger tumor volume; with mean tumor size of 17 ml (95% CI: 12–22 ml) in patients with low GDF-15 as opposed to mean tumor size of 27 ml (95% CI: 13–40 ml) in patients with high GDF-15 (p = 0.008)." (PMID 30645608, 2019). "Various conditions, such as pregnancy, tumor, neuronal damage, erythropoiesis, and cardiological status, were companied by increasing GDF-15 levels." (PMID 31772623, 2019). "GDF-15 reduces TNFα synthesis, and is followed by reduced TNFα-dependent tumor cell apoptosis and enhanced tumor growth." (PMID 30764482, 2019). "We found that PSA was preferentially variable in BPH, whereas GDF15 tended to vary in different tumor regions." (PMID 30090875, 2018). "In this study, we not only examined the levels of KLF5, GCN5, GDF15, C5aR, or C5a in NSCLC samples, but also evaluated the roles of KLF5, GCN5 and GDF15 in C5a-triggered cell proliferation in vitro and xenograft tumor growth in vivo." (PMID 29773900, 2018). "Our results appear vaguely similar to studies with the Apcmin/+ mouse model where deletion of the GDF-15 TGFβ-superfamily member reduced tumor suppression by the NSAID sulindac." (PMID 29560090, 2018). "The tumor microenvironment-derived GDF15 was also able to significantly increase cell survival in primary MM cells." (PMID 29724992, 2018). "Subsequently, we observed marked increase of KLF5, GCN5, and GDF15 expression in 185 NSCLC tumor tissues by immunohistochemical (IHC) staining." (PMID 29773900, 2018). "To our knowledge, we firstly demonstrate that chemotherapeutic damage of TACE to HCC promotes tumor angiogenesis through the release of GDF15." (PMID 29383859, 2018). "In the ADCA samples, GDF15 expression was elevated with a high degree of variation, indicating complex interactions between tumor cells and the microenvironment via modulators including GDF15." (PMID 30090875, 2018). "This indicates that depending on tumor cell changes, GDF-15 inhibits or enhances the migration and invasion of GBM cells." (PMID 29467963, 2018). "The cells treated with control shRNA rapidly developed into visible tumors, while knocking down of Gdf15 resulted in minimal tumor formation." (PMID 30542297, 2018). "In this study, we found that a new molecule GDF15 induced by chemotherapy damage to HCC is involved in tumor angiogenesis after TACE." (PMID 29383859, 2018). "At the same time, literature shows overexpression of GDF15 in tumors, which contradicts the tumor suppressor activity of GDF15." (PMID 30542297, 2018).
tumor (continued). "Although at the clinical cutoff of 35 U/ml for CA125, the sensitivity will decrease and specificity will increase, the result still indicated that serum GDF15 is a candidate sensitive tumor marker compared to CA125 for the detection of EOC." (PMID 29580231, 2018). "Early studies on GDF15 focused on the role of GDF15 in macrophage activation, growth inhibition, and apoptosis in tumor cells." (PMID 29967567, 2018). "Bruzzese F20 points out that the pro- and anti-tumor activities of GDF15 are highly dependent on the cellular and microenvironmental context." (PMID 29773900, 2018). "The present study showed that GDF15-overexpression in HeLa and SiHa cells enhanced tumor formation in vivo." (PMID 29636108, 2018). "Some data suggest that GDF15 has tumor suppressor activity, while other results suggests the opposite." (PMID 30542297, 2018). "We found that the GDF15-induced tumor sphere formation was inhibited by treatment with U0126 at a low dose (0.5 μM) and in a dose-dependent manner." (PMID 28206960, 2017). "We, therefore, focused on the ability of GDF15 to form tumor spheres, and examined the additional cell lines, T47D and MDA-MB-436 (MM436), which represent the luminal and basal subtype, respectively." (PMID 28206960, 2017). "Clinical data shows increased GDF15 levels in tumor tissues and serum, which correlate with reduced CRC overall survival." (PMID 29258163, 2017). "To investigate the possibility that GDF15 has any functions in CSCs, we performed tumor sphere formation assay." (PMID 28206960, 2017). "Studies reported that GDF15 inhibits proliferation of several cancer cell lines in vitro as well as suppresses tumor formation in vivo." (PMID 29069869, 2017). "GDF15-positive scoring correlated with high tumor grade (P=0.002), as approximately 75% of patients with high-grade tumors displayed a GDF15 score of 1+." (PMID 29212236, 2017). "Although several studies reported that GDF15 functions as a tumor suppressor by arresting the cell cycle and leading to apoptosis, there are numerous reports stating that GDF15 has a pro-tumorigenic ability." (PMID 28206960, 2017). "Subcutaneous xenotransplanted tumor and pulmonary metastatic animal models of LCSCs were established to further study the role of GDF15 in tumorigenesis and metastasis of LCSCs in vivo." (PMID 28199981, 2017). "The expression of platelet‐derived growth factor (PDGF)‐α, PDGF‐β, hepatocyte growth factor (HGF), and GDF‐15 increased in both the primary tumor site group and the micro metastasis group when HCCLM3 cells were cocultured with MSCs." (PMID 28205428, 2017). "The intuitive response is to consider the highly expressed GDF-15 protein as a driving factor in tumor growth." (PMID 28489602, 2017). "Treatment with U0126, an inhibitor of the MEK-ERK1/2 signaling, greatly inhibited the GDF15-induced tumor sphere formation." (PMID 28206960, 2017). "After 40 days, tumor incidence was detected in both the groups, and the volume and weight of the finally resected tumors in the GDF15 knockdown groups were significantly lower than those of the control group." (PMID 28199981, 2017). "Our studies demonstrated that tumor volume and weight in the GDF15 overexpression group were significantly higher than that of the control group, and GDF15 overexpression significantly increased the lung metastasis of SK-SCs." (PMID 28199981, 2017). "Clinical data showed GDF15 level in tumor tissues, and the serum was significantly increased, in which high GDF15 level correlated with a reduced overall survival in CRC." (PMID 26497212, 2016).
tumor (continued). "More interestingly, there was a significant correlation between GDF15 expression and tumor budding, which was considered as the cells with EMT phenotype in tumor tissues (P < 0.01)." (PMID 26497212, 2016). "In contrast, serum levels were significantly elevated in tumour patients for DcR3 (116.94 ± 57.37 fmol/ml) and GDF15 (164.44 ± 79.31 fmol/ml)." (PMID 25823874, 2015). "Our data indicates that TRAMP mice, overexpressing MIC-1/GDF15, have substantially increased survival due to decreased growth and histological grade of the primary tumor, further supporting a beneficial role for MIC-1/GDF15 in early cancer." (PMID 25695521, 2015). "Both TNC and GDF15 were found in the cytoplasm of the nevoid cells, with significantly higher expression levels in the tumor cells compared with normal cells." (PMID 26540631, 2015). "There is now a plethora of published data on the role of MIC-1/GDF15 on tumor growth and spread with a confusing range of results." (PMID 25695521, 2015). "During long-term treatment the GDF15 plasma levels in A2780cis-bearing mice increased rapidly with tumor growth, but were only slightly induced by long-term carboplatin treatment as compared to the GDF15 plasma levels in mice bearing the A2780 tumors." (PMID 25490861, 2015). "Growth differentiation factor 15 (GDF15) was identified as one of five potential resistance-related genes in the A2780cis tumor model." (PMID 25490861, 2015). "Serum concentrations in tumour samples were determined using the P2 fingerprint peptide for DcR3 and P1 for GDF15." (PMID 25823874, 2015). "Hypermethylation was associated with advanced tumor stage for ABCC6 (P = 0.050), BRCA1 (P = 0.032), CDH1 (P = 0.004), GDF15 (P = 0.005), HSPA2 (P = 0.000), RASSF1A (P = 0.003), TSHB1 (P = 0.018), and TMEFF2 (P = 0.002)." (PMID 25613404, 2015). "The apparently discordant effect of MIC-1/GDF15 on local tumor growth and the metastatic process, that we described previously, is again demonstrated here." (PMID 25695521, 2015). "Studies using transgenic models of spontaneously developing cancer that also bear genetically modified MIC-1/GDF15 expression and an intact immune system all point to a protective role for MIC-1/GDF15 on local tumor development." (PMID 25695521, 2015). "GDF-15 plays key regulatory roles in processes as diverse as cell cycle progression, differentiation, maintenance of pregnancy, apoptosis and tumor progression." (PMID 26243260, 2015). "Comparable to the measured GDF15 protein levels in serum, also the GDF15 transcript levels in tumour sections showed a clear distinction between both patient groups." (PMID 25823874, 2015). "Hypermethylation was associated with advanced tumor grade for BRCA1 (P = 0.003), CDH1 (P = 0.002), HSPA2 (P = 0.009), RASSF1A (P = 0.017), and THBS1 (P = 0.000), while methylated GDF15 (P = 0.002) promoter was associated with low tumor grade." (PMID 25613404, 2015). "This study clearly indicates that germline deletion of the MIC-1/GDF15 leads to increased local primary tumor growth resulting in earlier death of TRAMP PCa prone mice." (PMID 25695521, 2015). "The obtained qPCR values were specific, as GDF15 transcript levels from normal regions showed lower expression levels than those from tumour cells." (PMID 25823874, 2015). "In this study we identified GDF15 as potential resistance-related factor acting by maintaining a low proliferative and undifferentiated tumor phenotype through upregulation of p27Kip1 during carboplatin treatment." (PMID 25490861, 2015). "This reinforces the argument that MIC-1/GDF15 plays a protective role in early local tumor development and growth." (PMID 25695521, 2015). "Transcription of the TGFβ superfamily cytokine GDF15 (growth differentiation factor 15) is increased in multiple solid tumors, where it promotes tumor growth and confers resistance to several drugs such as bortezomib." (PMID 24548329, 2014).
tumor (continued). "Among the tumor-related proteins that we screened, GDF-15 was chosen for further study according to the homologous alignment analysis and cell-based ELISA results." (PMID 24236027, 2013). "By building tumor-bearing mouse models, we demonstrate that GDF-15 can inhibit the ability of DCs to stimulate a tumor-specific immune response in vivo." (PMID 24236027, 2013). "In PCa, an increased amount of MIC-1/GDF15 localized to the tumor improves patient outcome, especially in those with a Gleason sum score of 6 or less." (PMID 22952779, 2012). "The majority of studies have suggested that MIC-1/GDF15 has anticancer activity and induces tumor cell apoptosis." (PMID 22952779, 2012). "Overall, these data suggested that TRAMPfmsmic-1 mice have a larger proportion of the prostate at a lower tumor grade than TRAMP mice, indicating the MIC-1/GDF15 overexpression slows local tumor evolution." (PMID 22952779, 2012). "Growth/differentiation factor-15(GDF-15) is a divergent TGFβ family member that has been implicated in inhibition of tumor growth and increased tumor invasiveness." (PMID 22347457, 2012). "This tumor expression of MIC-1/GDF15 is often reflected in its blood levels, which increase with cancer development and progression, generally in proportion to the stage and extent of disease." (PMID 22952779, 2012). "A nonsignificant trend of elevated plasma levels of GDF15 was observed in tumours with increasing intensity (P=0.148) and fraction (P=0.326) of GDF15 expression as assessed by immunohistochemistry." (PMID 21468045, 2011). "High expression of GDF15 in tumour tissue and high plasma levels correlate with an increased risk of recurrence and reduced overall survival." (PMID 21468045, 2011). "No other histopathological or clinical parameters were correlated with the intensity or fraction of GDF15 in the tumour." (PMID 21468045, 2011). "Tumours expressing moderate or high intensity of GDF15 were less likely to have vascular invasion (P=0.036)." (PMID 21468045, 2011). "For example, TSP1, CYP1A1, and GDF15 mRNA induction are most likely reflecting a direct inducing effect on the tumor cells, because elevated mRNA levels were also achieved in vitro in cell cultures where no other cell types were present." (PMID 20470445, 2010). "Growth differentiation factor-15 (PLAB\MIC-1\GDF-15) shows a striking correlation between expression level and metastatic phenotype in several tumor types." (PMID 18442402, 2008). "The major function of GDF15 is still uncertain, but there are indications that it plays a role in growth inhibition and induction of apoptosis in several tumour cell lines." (PMID 15900300, 2005). "Collectively, the cellular source of GDF15 could determine its effect on tumor progression, with GDF15+ macrophages exerting an antitumor role in OSCC, whereas secreted GDF15 exerting a protumor role." (PMID 41824793, 2026). "Mechanistically, macrophage-intrinsic GDF15 could enhance the abilities to phagocyte tumor cells and to cross-present antigens to CD8+ T cells." (PMID 41824793, 2026). "Tumor cell-derived serum GDF15 levels are elevated in mice bearing these tumors." (PMID 41617691, 2026). "GDF15 promotes tumor cell invasion and metastasis by regulating cell migration and apoptosis." (PMID 40190762, 2025). "However, analysis of oxidative-stress-related pathways showed that tumor cells with high GDF15 expression only exhibited a weak oxidative stress advantage." (PMID 41035818, 2025). "However, CD10, KHDRBS3, PCLAF, PSMA, SIK2 and GDF15 were differentially expressed with PCa progression, emphasising their roles in promoting tumour growth, invasion and metastasis." (PMID 39578642, 2025). "Univariate analysis showed that tumor number (p = 0.0001), microvascular invasion (p = 0.014), extrahepatic metastasis (p = 0.002), AST (p = 0.034), CRP (p = 0.003), BCLC stage C (p = 0.038), and serum GDF15 (p = 0.009) were significantly associated with OS." (PMID 40677718, 2025).